SHOC1 (shortage in chiasmata 1)
Description:
ATPase required during meiosis for the formation of crossover recombination intermediates (By similarity). Binds DNA: preferentially binds to single-stranded DNA and DNA branched structures. Does not show nuclease activity in vitro, but shows ATPase activity, which is stimulated by the presence of single-stranded DNA. Plays a key role in homologous recombination and crossing-over in meiotic prophase I in male and female germ cells (By similarity). Required for proper synaptonemal complex assembly and homologous chromosome pairing (By similarity). Requiref for recruitment TEX11 and MSH4 to recombination intermediates (By similarity).
Synonyms: MZIP2; C9orf84; ZIP2; FLJ32779; SPGF75; ZIP2H
Tractability: No criterion of Open Targets' tractability assessment is met for any kind of drug.
Gene: Protein-coding gene on chromosome 9 (111,686,171 to 111,795,008, reverse strand). Ensembl gene ENSG00000165181.
Subcellular location: Chromosome
Subcellular location (Human Protein Atlas): Nucleoplasm; Nuclear bodies
Gene Ontology:
Molecular function: ATP hydrolysis activity; single-stranded DNA binding
Biological process: homologous chromosome pairing at meiosis; meiotic DNA double-strand break formation; reciprocal meiotic recombination; resolution of meiotic recombination intermediates; spermatogenesis; synaptonemal complex assembly
Cellular component: chromosome; condensed nuclear chromosome; recombination nodule
Genetic constraint (gnomAD): Loss-of-function variants: 56 observed, 78.41 expected, observed/expected ratio (o/e) 0.71, 90% interval 0.57 to 0.89. The synonymous counts are far from expectation, so gnomAD's model fits this gene poorly and the ratio says little. Missense variants: 805 observed, 922.64 expected, observed/expected ratio (o/e) 0.87, 90% interval 0.82 to 0.93. Synonymous variants: 255 observed, 319.21 expected, observed/expected ratio (o/e) 0.8, 90% interval 0.72 to 0.89.
Homologues: Orthologues: macaque SHOC1 (95% identical), chimpanzee SHOC1 (94% identical), pig SHOC1 (75% identical), rabbit SHOC1 (68% identical), guinea pig SHOC1 (62% identical), mouse Shoc1 (59% identical), rat Shoc1 (59% identical), tropical clawed frog shoc1 (31% identical), dog SHOC1 (23% identical).
Diseases named in the same sentence as SHOC1 in open-access papers:
SHOC1 is named in the same sentence as 6 diseases in open-access papers, as found by Europe PMC text mining. Sharing a sentence is not in itself a finding about the gene and the disease. The quoted sentences say what the papers report.
male infertility (1 paper, 2026). The inability of the male to effect fertilization of an ovum after a specified period of unprotected intercourse. "Although genetic variants of SHOC1 are clinically associated with male infertility, their conserved functions in human gametogenesis remain enigmatic." (PMID 42258546, 2026).
SHOC1 also shares sentences with these, for which no sentence is quoted: Azoospermia (2 papers); infection (1); Obesity (1); Premature ovarian insufficiency (1); stomach carcinoma (1).